LINC02218 (long independently transcribed non-coding RNA 2218)
Gene: Protein-coding gene on chromosome 5 (17,444,010 to 17,487,371, forward strand). Ensembl gene ENSG00000249662.
Gene Ontology:
Molecular function: RNA polymerase II general transcription initiation factor activity; protein heterodimerization activity
Biological process: RNA polymerase II preinitiation complex assembly; transcription initiation at RNA polymerase II promoter
Cellular component: transcription factor TFIID complex; nucleus
Homologues: Orthologues: chimpanzee LINC02218 (97% identical), tropical clawed frog taf11 (47% identical), zebrafish taf11 (47% identical), Drosophila melanogaster Taf11 (44% identical), Caenorhabditis elegans taf-11.1 (35% identical), Caenorhabditis elegans taf-11.2 (31% identical). Paralogues in human: TAF11L12 (92% identical), TAF11L2 (92% identical), TAF11L13 (89% identical), TAF11L11 (89% identical), TAF11L10 (88% identical), TAF11L5 (88% identical), TAF11L6 (88% identical), TAF11L7 (88% identical), TAF11L8 (88% identical), TAF11L3 (87% identical), TAF11L4 (87% identical), TAF11L9 (87% identical), and 2 more.